STAU1 (staufen double-stranded RNA binding protein 1)
Diseases named in the same sentence as STAU1 in open-access papers (continued):
Sharing a sentence is not in itself a finding about the gene and the disease.
osteosarcoma (2 papers, 2014 to 2021). A usually aggressive malignant bone-forming mesenchymal neoplasm, predominantly affecting adolescents and young adults. "Fluctuation of Stau1 levels through the cell cycle was confirmed in the human U2OS osteosarcoma cell line." (PMID 24906885, 2014).
breast carcinoma (1 paper, 2021). "In this study, we for the first time analyzed the relationship between TINCR and the clinicopathological characteristics of breast cancer patients, as well as verified the binding between TINCR and STAU1 in breast cancer cells." (PMID 33649294, 2021).
cervical cancer (1 paper, 2023). A primary or metastatic malignant neoplasm involving the cervix. "The authors proposed a mechanism for the action of LncCCLM in cervical cancer, according to which cytoplasmic LncCCLM interacts with Staufen double-stranded RNA binding protein 1 (STAU1) to promote the decay of the insulin-like growth factor 1 (IGF-1) mRNA." (PMID 37407839, 2023).
Glucose intolerance (1 paper, 2024). Glucose intolerance (GI) can be defined as dysglycemia that comprises both prediabetes and diabetes. "In the in vivo mice model, GIGYF2 knockdown and tocopherol administration alleviate high-fat diet (HFD)-induced glucose intolerance and IR, along with the suppression of STAU1/PTEN and restoration of PI3K/AKT signaling." (PMID 39138413, 2024).
hepatoma (1 paper, 2014). "Our results are in agreement with those of a large-scale screen in which Stau1 significantly inhibited colony formation when transfected in human hepatoma cells." (PMID 24906885, 2014).
HIV-1 infection (1 paper, 2021). The type species of lentivirus and the etiologic agent of acquired immunodeficiency syndrome (AIDS). "Although a similar regulatory pathway was not reported in STAU1, its homolog STAU2 could act as a positive regulator that interacts with HIV-1 Rev to promote HIV-1 infection." (PMID 34452292, 2021).
large cell carcinoma (1 paper, 2021). A malignant epithelial neoplasm composed of large, atypical cells. "Stau1 expression was on average 2.73-fold higher (p = 9.03 × 10−4) in large cell carcinoma compared to normal tissues and 2.22 (p = 1.80 × 10−4) and 2.16 (p = 2.33 × 10−4) fold higher in adenocarcinoma cells and squamous carcinoma cells, respectively." (PMID 35008641, 2021).
lung carcinoma (1 paper, 2021). "In the present study, we show that Stau1 expression is upregulated in non-small cell lung cancer and that high Stau1 expression is associated with better survival rate of patients with lung cancer." (PMID 35008641, 2021). "To establish a link between Stau1 expression and lung cancer, we first quantified Stau1 expression at the protein level in adjacent normal (N) and tumor tissues (T) of non-small cell lung patients." (PMID 35008641, 2021). "Here, we observed that lung cancer patients with a high Stau1 expression have a longer recurrence free survival." (PMID 35008641, 2021). "Altogether, these results indicate that the high Stau1 expression observed in lung cancer prevents cancer cells from acquiring migratory ability." (PMID 35008641, 2021). "Using shRNA as a means to downregulate Stau1 expression in the H460 lung cancer cell line, we showed that Stau1 depletion enhances cell migration and invasiveness in vitro and facilitates tumor development and metastasis in mice." (PMID 35008641, 2021). "Altogether, our results suggest that regulation of THBS1 expression by Stau1 may be a key process involved in lung cancer progression." (PMID 35008641, 2021).
myelodysplastic syndrome (1 paper, 2023). A clonal hematopoietic disorder characterized by dysplasia and ineffective hematopoiesis in one or more of the hematopoietic cell lines. "In myelodysplastic syndromes (MDS) and AML, the dsRNA-binding protein Staufen1(Stau1) stabilized ERV RNA via forming a lncRNA TINCR-Stau1-ERV complex." (PMID 37662910, 2023).
neuroblastoma (1 paper, 2021). Neuroblastoma (NB) is the most common solid, extracranial childhood tumor. "In this context, the role of STAU1 in differentiation of the human neuroblastoma cell line SH-SY5Y and dendritic development has been studied by various groups." (PMID 34633481, 2021). "Several studies also emphasized the anti-apoptotic role of STAU1 via the control of mRNA stability and translation in neuroblastoma cells." (PMID 34633481, 2021). "Given the critical role of SIRT1 in the NAD+ pathway and its importance in the control of cell differentiation, apoptosis, autophagy, metabolism, and stress response, STAU1 may indirectly regulate fate of neuroblastoma cells through controlling SIRT1 levels." (PMID 34633481, 2021).
non-small cell lung carcinoma (1 paper, 2021). A group of at least three distinct histological types of lung cancer, including non-small cell squamous cell carcinoma, adenocarcinoma, and large cell carcinoma. "Accordingly, from the meta-analysis of available databases, we highlight a clinical relevance of Stau1 expression for patients with non-small cell lung cancer." (PMID 35008641, 2021). "Accordingly, we decided to further investigate Stau1 function at the cellular and molecular levels by using the non-small cell lung cancer cell line H460." (PMID 35008641, 2021). "To make sense of these observations, we next examined the correlation between Stau1 expression and non-small cell lung cancer outcome using the online Kaplan–Meier plotter set of data (kmplot.com, accessed on 15 July 2021)." (PMID 35008641, 2021). "Taken together, these data indicate that a high level of Stau1 confers a better clinical outcome to non-small cell lung cancer patients particularly for the adenocarcinoma subgroup." (PMID 35008641, 2021). "To this aim, we compared Stau1 expression level of 156 samples of non-small cell lung cancer issued from the Hou study." (PMID 35008641, 2021). "To investigate the clinical relevance of Stau1 expression level in non-small cell lung cancer patients, we performed a meta-analysis of published gene expression data using the OncomineTM database (Compendia Bioscience, Ann Arbor, MI, USA)." (PMID 35008641, 2021). "In addition, the anti-metastatic phenotype is consistent with the meta-analysis of patients with non-small cell lung cancer that links high expression of Stau1 to a better clinical outcome (KMplot)." (PMID 35008641, 2021). "Thus, Stau1 expression is misregulated in samples of patients with non-small cell lung cancer." (PMID 35008641, 2021).
pancreatic cancer (1 paper, 2023). "Interestingly, STAU1 has been related with pancreatic cancer and its misregulation impacts cell cycle regulation, showing the potential of this protein to also be involved in COREAD progression." (PMID 37384253, 2023).
renal carcinoma (1 paper, 2024). A carcinoma arising from the epithelium of the renal parenchyma or the renal pelvis. "In renal cancer, lncTCL6 attenuates cancer progression by suppressing Src-AKT driven metastatic pathway via STAU1-mediated Src mRNA decay." (PMID 39138413, 2024).
squamous carcinoma (1 paper, 2021). "The analysis of Stau1 expression in adenocarcinoma (HR = 0.38; 95% CI = 0.29–0.5; p= 3.5 × 10−13), and on squamous cell carcinomas (HR = 0.76; 95% CI = 0.6–0.96; p = 0.023) provided similar results, although the difference was less pronounced for squamous cell carcinomas." (PMID 35008641, 2021).
cancer (14 papers, 2014 to 2026). A tumor composed of atypical neoplastic, often pleomorphic cells that invade other tissues. "In this section, we focus on the molecular mechanisms underlying STAU1-mediated control of cell functions and highlight its plausible effects on human cancer." (PMID 34633481, 2021). "In this context, the significance of STAU1 in the pathogenesis of cancer has been reported to be linked to its role in the regulation of mRNA translation, splicing, and decay." (PMID 34633481, 2021). "Our results point out for the first time to the possibility that Stau1 participates in a mechanism of post-transcriptional regulation of gene expression that is linked to cell cycle progression in cancer cells." (PMID 24906885, 2014). "Accordingly, when analyzed with the Genetic Association Database program, 19 and 14 of the Stau1-bound mRNAs were linked to metabolic diseases and cancer, respectively." (PMID 24906885, 2014). "In this review, we focus on the role of STAU1 in cell functions linked to cancer." (PMID 34633481, 2021). "The critical importance of cell growth control mechanisms in cancer progression accompanied by the observed roles of STAU1 in cell growth, led to recent investigations on the impact of STAU1 on cell growth linked to the pathophysiology and treatment of various cancers." (PMID 34633481, 2021). "Given this, dysregulation of STAU1’s expression and/or function has been linked with disrupted cellular functions and with the pathophysiology of several diseases including neurodegenerative and neuromuscular disorders, as well as cancer." (PMID 34633481, 2021). "Our results highlighted a novel molecular mechanism associated with the functions of a cytoplasmic lncRNA, via STAU1 activity, during cancer metastasis; this could thus comprise a potential therapeutic target for cancer." (PMID 34163032, 2021). "However, further studies may focus on detecting the direct interaction between STAU1 and the mRNAs of the apical–basal polarity markers (e.g., Crumbs3, Pals1, and Pals1-associated tight junction protein, Patj) in cancer cells." (PMID 34633481, 2021). "In CRC, SNHG5 interacts with the double-stranded RNA-binding protein Staufen1 (STAU1), preventing STAU1-mediated degradation of specific mRNAs and thereby stabilizing transcripts critical for cancer cell survival." (PMID 41550840, 2026). "Dysregulated STAU1-mediated post-transcriptional genetic modulation appears to regulate apoptosis while also being a pivotal occurrence in cancer progression." (PMID 35350787, 2022). "Staufen1 (STAU1) is an RNA-binding protein whose expression level is critical in cancer cells as it is related to cell proliferation or cell death." (PMID 36232890, 2022). "In this paper, we show that a modest increase in STAU1 expression in cancer cells triggers apoptosis as early as 12 h post-transfection and impairs proliferation in non-apoptotic cells for several days." (PMID 35806349, 2022). "STAU1-mediated mRNA decay has been shown to also play a significant role in the control of cancer cell proliferation." (PMID 34633481, 2021). "We also highlight the link between STAU1-mediated control of cellular functions and cancer development, progression, and treatment." (PMID 34633481, 2021). "Taken together with other data showing a correlation between STAU1 levels and advanced stages of cancer, these findings suggest a promising cancer-specific role for STAU1 in the regulation of tumor metastasis." (PMID 34633481, 2021). "In conclusion, our results highlight a novel mechanism of cytoplasmic lncRNA SPRY4-IT1 in which SPRY4-IT1 affecting TCEB1 mRNA stability via STAU1-mediated degradation during cancer metastasis." (PMID 34163032, 2021). "Since cell migration is a critical step in tumor progression, several studies uncovered role of STAU1 in the regulation of cell migration during cancer development and tumorigenesis." (PMID 34633481, 2021).
cancer (continued). "In this regard, STAU1 has been shown to regulate cancer cell migration, positively or negatively, through different mechanisms." (PMID 34633481, 2021). "More specially, we highlight the impact of STAU1 expression/dysregulation on the development and prognosis of cancers leading to the notion that STAU1 is a novel disease biomarker and therapeutic target for cancer." (PMID 34633481, 2021). "An increasing number of studies show that misregulation of Stau1 expression affects the delicate balance between oncogene, tumor-suppressor, and pro- and anti-apoptotic gene expression and favors cancer development." (PMID 35008641, 2021). "Our study describes the role of the lncRNA SPRY4 intronic transcript 1 (SPRY4-IT1) in cancer metastasis by mechanisms related to Staufen1 (STAU1)-mediated mRNA decay (SMD)." (PMID 34163032, 2021). "Among these RBPs, Stau1 appears as a key component of cancer development, as there is increasing evidence establishing a correlation between the deregulation of its expression and tumor progression." (PMID 35008641, 2021). "In particular, there has been increasing attention on the role of STAU1 in neuromuscular disorders, neurodegeneration, and cancer." (PMID 34633481, 2021). "In cancer cells, it is rather STAU1 overexpression that impairs cell proliferation." (PMID 35806349, 2022). "Given the multifunctional nature of STAU1 in controlling cellular differentiation, STAU1 dysregulation may positively or negatively impact cancer cell differentiation and contribute to the severity of the disease." (PMID 34633481, 2021). "In this context, STAU1 may exhibit tumor suppressor or oncogenic effect depending on the source and type of cancer stem cells as well as the type of tissues to which stem cells are destined to differentiate." (PMID 34633481, 2021). "Therefore STAU1 has been suggested as a novel therapeutic target for the inhibition of cancer metastasis." (PMID 34633481, 2021). "In this case, STAU1 downregulation may inhibit cancer cell survival by preventing SG formation under stress." (PMID 34633481, 2021). "We found two subpopulations of cancer cells showing either high or low Stau1 expression." (PMID 35008641, 2021). "Interestingly, expression of Thrombospondin1 (THBS1) mRNA, one of the previously identified targets in cancer progression, is significantly increased in Stau1-depleted cells." (PMID 35008641, 2021). "Hence, our review emphasizes the potential of STAU1 as a novel biomarker and therapeutic target for cancer diagnosis and treatment, respectively." (PMID 34633481, 2021). "Given the essential roles of STAU1 in these processes and the importance of cell differentiation in cancer development, STAU1 dysregulation may further impact cancer progression through controlling cellular differentiation." (PMID 34633481, 2021). "For instance, the direct role of STAU1 in upregulating the mTOR pathway may positively impact formation of SGs and further promote cancer cell growth and survival." (PMID 34633481, 2021). "Therefore, genetic silencing of STAU1 in these cells reduced cell metastasis and inhibited cancer progression." (PMID 34633481, 2021). "Accordingly, the role of STAU1 in these signaling pathways may indirectly impact cell polarity and cancer development." (PMID 34633481, 2021). "In the current review, we focus on the role of STAU1 in cell functions and cancer development." (PMID 34633481, 2021). "Given the importance of STAU1 in developing and maintaining cell polarity, its dysregulation may affect cell polarity and impair asymmetric cell division thereby promoting cancer development and progression." (PMID 34633481, 2021). "STAU1 can also regulate cancer cell survival through translational regulation." (PMID 34633481, 2021).
cancer (continued). "Given the available evidence on the role STAU1 in the control of two main autophagy regulatory pathways, mTOR and JNK, as well as its direct binding to ATG mRNAs, further studies are necessary to determine the exact role of STAU1 in autophagy control of normal and cancer cells." (PMID 34633481, 2021). "The pro-apoptotic function of STAU1 has been also observed in cancer." (PMID 34633481, 2021). "Hence, genetic silencing of STAU1 in vitro reduces growth of cancer cells and inhibits tumor formation in vivo." (PMID 34633481, 2021). "Although it may be too early to generalize to all cancers and untransformed cells, our data suggest that Stau1 may restore, at least partly, some pathways that had been modified and/or overcome to allow unregulated proliferation of cancer cells." (PMID 24906885, 2014). "Therefore, a modification of Stau1 expression and/or activity has disastrous consequences since Stau1 is a key regulator of various mRNA regulons that are critical for cell cycle regulation, and their misregulation triggering cancer development and progression." (PMID 35008641, 2021). "Therefore, STAU1 level may inhibit myogenesis in cancer stem cells, and hence, promote muscle-related cancers." (PMID 34633481, 2021). "Also, based on the available evidence on the crucial impact of STAU1 on both cell polarity and differentiation, STAU1 may play important roles in maintaining a balance between pluripotency and differentiation properties of stem-like cancer cells." (PMID 34633481, 2021). "However, the apparent distinct roles of STAU1 in controlling apoptosis among various cancer types may ultimately determine its differential impact as either an oncogene or tumor suppressor." (PMID 34633481, 2021). "We further summarized six genes (IGF2BP3, LYAR, RALY, STAU1, SYNCRIP, and TOP1) that displayed high correlations between mRNA and protein expression in both cancer and cell line databases." (PMID 36428700, 2022). "For example, STAU1 and YTHDF1 were highly altered across stages in both carcinomas." (PMID 37384253, 2023). "Strikingly, the phenotypes due to Stau1 overexpression are observed in three cancer cell lines but not in two untransformed cells." (PMID 24906885, 2014). "Moreover, SPRY4-IT1 was found to bind STAU1, promote STAU1 recruitment to the 3′-UTR of TCEB1 mRNA, and affect TCEB1 mRNA stability and expression, resulting in hypoxia-inducible factor 1α (HIF-1α) upregulation, and thereby affecting cancer cell metastasis." (PMID 34163032, 2021). "Therefore, the direct or/and indirect impact of STAU1 on cell polarity, EMT, and cell–cell adhesion may contribute to the poor-differentiation phenotype of cancer cells and disease severity." (PMID 34633481, 2021). "On the contrary, based on the available evidence on the negative impact of STAU1 levels on SG formation in myoblast, STAU1 may alternatively function as a tumor suppressor in some cancers by inhibiting SG formation." (PMID 34633481, 2021).